DROSHA (drosha ribonuclease III)
Diseases named in the same sentence as DROSHA in open-access papers (continued):
Sharing a sentence is not in itself a finding about the gene and the disease.
tumor (55 papers, 2004 to 2026). "Recent studies further demonstrate that DROSHA mutations in WT, as well as DROSHA silencing in vitro, are associated with a mesenchymal-like state and the dysregulation of redox metabolism, suggesting broader effects on tumor biology beyond miRNA processing." (PMID 40722750, 2025). "Further BCOR variants were found in a PB-miRNA2 case with a homozygous DROSHA deletion (BCOR S17R; VAF = 100%, uncertain significance of pathogenity) and in a PB-miRNA1A tumor with a heterozygous DROSHA mutation (BCOR P120 frameshift deletion; VAF = 18%)." (PMID 41291966, 2025). "Low DICER1 expression was significantly correlated with advanced tumor stages (p = 0.007), whereas low DROSHA expression was associated with suboptimal surgical cytoreduction outcomes (p = 0.02)." (PMID 39596271, 2024). "These mutations, occurring in the RNase IIIb domain of DROSHA, disrupt metal ion binding and endonuclease activity, leading to the reduced level of several miRNAs, including the tumor suppressor let-7 family." (PMID 39457367, 2024). "While AGO1 and DGCR8 mutations conferred around 2.5 times higher risk of advanced tumor size, DROSHA mutations were 2.5 times more likely to present with poorly differentiated tumors at the time of diagnosis." (PMID 36672288, 2023). "The tumor cohorts had been screened in parallel for DROSHA E1147K mutations that are found in high-risk blastemal WT (and R. Vardapour, pers." (PMID 34689785, 2021). "A group of 66 tumours were assessed for a panel of 162 miRNAs using quantitative PCR and low expression of DICER and DROSHA were identified in high-risk tumours." (PMID 28103887, 2017). "Although numerous studies have shown that tumor size is of no prognostic significance in CRC, our data showed that DROSHA rs10719 CC was associated with an increased CRC risk regarding tumor size (<5 cm) and age (≥62 years)." (PMID 26147304, 2015). "The tumor from P03 presented a mutation in DROSHA (c.3665A > G, p.Glu1222Gly) with a VAF of 32%." (PMID 32592321, 2020). "In contrast, heterozygous mutations in the RNase IIIB domain of DROSHA exhibit a dominant negative effect, significantly impairing the production of the let-7 family and other miRNAs while still permitting enough residual miRNA processing to support tumor growth." (PMID 39457367, 2024). "Overall, our data suggest that in a fraction of relapsing WT patients SIX1 and DROSHA mutations might be (whether spatially or temporally) heterogeneous events within the primary tumor, which are positively selected in the process of tumor progression to recurrence." (PMID 26802027, 2016). "DROSHA acts as a context-dependent regulator, functioning as a tumor suppressor in some cases while contributing to tumor progression through miRNA expression changes in others." (PMID 40136480, 2025). "The three studied DROSHA SNPs in this study have also been investigated in other types of neoplasia, including chronic lymphoblastic leukemia (CLL)." (PMID 40699872, 2025). "Tumor samples exhibiting both high DICER1 and DROSHA expression were linked to improved median survival rates." (PMID 39596271, 2024). "In conclusion, DROSHA rs10719 and DICER rs3742330 polymorphisms are associated with increased BC risk and more prevalent in tumor tissue among our cohort, suggesting a potential role in miRNA dysregulation during breast tumorigenesis." (PMID 39329954, 2024). "The results of the research conducted so far on the role of DROSHA expression in the pathogenesis of other neoplastic diseases are also contradictory." (PMID 34885248, 2021). "An insignificantly higher (tendency to significance, p = 0.053) relative methylation level of DROSHA (region 2) was found in patients with larger tumours." (PMID 34885248, 2021). "Our data add to this scenario the possibility that alterations of the SIX1 and DROSHA genes occur also at later stage, driving tumor evolution toward chemotherapy resistance and recurrence." (PMID 26802027, 2016).
tumor (continued). "Sufficient DNA was available on 16/19 MLLT1-mutant tumours to perform mutation analysis for WT1, CTNNB1, WTX, DROSHA, DGCR8, and SIX1/2 and this revealed five CTNNB1 mutations, one WTX mutation, and no WT1 DROSHA, DGCR8, or SIX1/2 mutations." (PMID 26635203, 2015). "DROSHA has tumor suppressor or oncogenic activity, depending on the type of tumor." (PMID 30545127, 2018). "Similarly, we observed that DROSHA rs10719 and RAN rs14035 CC genotypes were associated with CRC with respect to the subjects’ tumor sizes." (PMID 26147304, 2015). "Aberrant expression of miRNA biosynthesis genes DGCR8 and DROSHA are described to promote tumorigenesis as it results in aberrant miRNA expressional pattern that could be at play even at the level of tumour initiation, by downregulating tumour suppressor genes or overexpressing oncogenes." (PMID 36499151, 2022). "Finally, in P03, the mutation in DROSHA (c.3665A > G, p.Glu1222Gly), detected in tumor with VAF of 32.00%, was not identified in the baseline samples." (PMID 32592321, 2020). "In HCC, DROSHA and DICER are often downregulated, contributing to global miRNA dysregulation and aggressive tumor behavior." (PMID 40943288, 2025). "Specific miRNAs that DROSHA and DICER can potentially impact include oncogenic miRNAs like miR-21 and tumor suppressor miRNAs such as let-7." (PMID 39329954, 2024). "We transfected codon-optimized LT (LTco), tumor-derived truncated LT (LT339), and codon-optimized sT (sTco) into MCPyV− MCC cell lines and evaluated the effect on expression levels of DROSHA, DGCR8, DICER1, and TARBP2 using western blotting." (PMID 34761184, 2021). "We observed significant over-expression of ADAR, ADARB1, DDX5/17/20, DGCR8, DICER1, DROSHA, EIF2C1-4 (AGO1-4), GEMIN4, POLR2A, TARBP2, TNRC6A and XPO5 in tumor tissue compared to adjacent mucosa." (PMID 31510013, 2019). "In this sense, Drosha, a component of miRNA biogenesis, has been reported to be downregulated in response to tumor hypoxia through a process mediated by the direct binding of the hypoxia-responsive transcription factors ETS1 and ELK1 to the promoter of DROSHA." (PMID 30842790, 2019). "DROSHA-rs10719 and SMAD3-rs17228212 had an opposite detrimental effect on pathological tumour response (p=0.0274, p=0.0049)." (PMID 26934318, 2016). "We also observed significant changes in AGO2, DICER1 and DROSHA expression in relation to ER status, with AGO2 and DROSHA being higher and DICER1 lower in ER- tumor samples." (PMID 17922911, 2007). "Moreover, pri‐miR‐93‐1/‐2 and the miRNA‐processing enzymes DROSHA and DICER1 were undetectable in RBCs, whereas mature miR‐93‐5p increased after exposure to tumor‐derived exosomes (p < 0.05)." (PMID 41159542, 2026). "In addition, the expression of DDX5/20, DGCR8, DICER1, DROSHA, EIF2C1-4, GEMIN4, TNRC6A and XPO5 was deregulated not only in tumor tissue, but also in corresponding liver metastases compared to adjacent tissue." (PMID 31510013, 2019). "Two tumours with MLLT1 mutations also had CTNNB1 mutations; no MLLT1-mutant tumours had accompanying WT1, WTX, DROSHA, DGCR8, SIX1, or SIX2 mutations." (PMID 26635203, 2015). "As expected, we confirmed in individual tumor samples of our patients an inverse correlation of these target mRNA and miR-107 expression levels, being this correlation significant for CCND1, DICER1, DROSHA and NFKB1." (PMID 25197016, 2014). "As we found many changes in miRNA expression across the five clinical tumor subtypes we had defined above, we asked whether DICER1, DROSHA, DGCR8, AGO1, AGO2, AGO3 or AGO4 expression differs among these subgroups." (PMID 17922911, 2007).
tumor (continued). "Furthermore, key regulators of the miRNA pathway, including DROSHA, DGCR8, AGO1 and AGO2 are frequently overexpressed—rather than downregulated—in HCC, and specifically AGO2 overexpression has been shown to promote HCC progression, tumor vascularization and metastasis." (PMID 31732746, 2019). "Finally, there are also several studies describing neither significant difference in the expression of DICER1, DROSHA and EIF2C2 between tumor tissue and adjacent mucosa, nor in the correlation of miRNAs biogenesis genes expression with clinical-pathological features of the patients." (PMID 31510013, 2019).
infection (19 papers, 2011 to 2025). The state of being infected such as from the introduction of a foreign agent such as serum, vaccine, antigenic substance or organism. "The three cell types were infected with the SARS-CoV-2 delta variant at an MOI of 0.1, and mRNA expression levels of AGO2, DICER1, DGCR8, DROSHA, and XPO5 were measured 24 h and 48 h after infection." (PMID 37243263, 2023). "In another study, infection of A549 cells with dengue virus 4 resulted in reduced mRNA levels of DICER, DROSHA, and DGCR8." (PMID 37243263, 2023). "Another example is that infection with Kaposi’s sarcoma-associated herpesvirus (KSHV) resulted in increased expression of DICER1 mRNA in primary human umbilical vein endothelial cells, whereas mRNA expression levels of DGCR8, DROSHA, and XPO5 did not change significantly." (PMID 37243263, 2023). "As expected, increased levels of phosphorylation of IRF3 and STAT1 were found in AGO2 knockout cells after infection with DelNS1 WSN virus, regardless of the presence of DROSHA." (PMID 40949099, 2025). "The results showed that infection of NHBE and Calu-3 cells with SARS-CoV-2 did not impact mRNA expression levels of AGO2, DICER1, DGCR8, DROSHA, and XPO5 at 24 and 48 h post infection, in good concordance with our results on patient samples." (PMID 37243263, 2023).
neurodegenerative disease (3 papers, 2017 to 2023). A disorder of the central nervous system characterized by gradual and progressive loss of neural tissue and neurologic function. "Emerging evidence suggests that polymorphism(s) in these genes (DICER1 and DROSHA) may alter the biological functions of miRNAs and contribute to the pathogenesis of various systemic and neurodegenerative diseases." (PMID 37099569, 2023).
hematologic malignancies (1 paper, 2025). "Consistent with previous reports of their association with poor prognosis in solid tumors, our findings extend the relevance of DICER1 and DROSHA alterations to hematologic malignancies as well." (PMID 41463093, 2025).
DROSHA also shares sentences with these, for which no sentence is quoted: Alzheimer disease (3 papers); spinal muscular atrophy (3); acute myeloid leukemia (2); cancer of the head and neck (2); nasopharyngeal carcinoma (2); rectal cancer (2); abortion (1); acute lymphoblastic leukemia (1); adenocarcinoma (1); adenomyosis (1); angiosarcoma (1); autoimmune disease (1); Azoospermia (1); clear cell renal cell carcinoma (1); congenital heart disease (1); Dengue virus infection (1); frontotemporal lobar degeneration (1); gallbladder adenocarcinoma (1); Global developmental delay (1); GLOW syndrome (1); heart failure (1); hypothyroidism (1); inflammation (1); Intellectual disability (1); leukemia (1); Macrocephaly (1); microcephaly (1); multiple sclerosis (1); neurological diseases (1); oesophageal cancer (1).
A further 11 diseases each share a sentence with DROSHA in 1 paper.